CGAS (cyclic GMP-AMP synthase)
Diseases named in the same sentence as CGAS in open-access papers (continued):
Sharing a sentence is not in itself a finding about the gene and the disease.
metabolic disorders (continued). "Abnormal mitochondrial homeostasis can lead to cytosolic mtDNA leakage, which promotes the activation of the cGAS-STING pathway and triggers a chronic sterile inflammatory response, facilitating the processes of aging, metabolic disorders, and autoimmune diseases." (PMID 39891248, 2025). "Moreover, potential inhibitors of the cGAS-STING pathway and therapeutic prospects against metabolic diseases are discussed." (PMID 38164186, 2024). "Therefore, further studies are needed to fully elucidate the complex molecular mechanisms linking the cGAS-STING pathway and inflammation in diverse etiological contexts of metabolic disorders." (PMID 37762143, 2023). "This suggests that long-term HIIT may exert immune regulation and play an anti-inflammatory role by activating the cGAS-STING signaling pathway, thus effectively alleviating metabolic disorder phenotype." (PMID 37762143, 2023). "Although these studies have found an association between the Akt protein family and the cGAS–STING pathway in different diseases, none of them is direct evidence of a direct link between the Akt protein family and cGAS–STING in metabolic diseases." (PMID 34906241, 2021). "The cGAS-STING pathway activated by double-stranded DNA (dsDNA), cyclic dinucleotides (CDNs), endoplasmic reticulum stress (ER stress), mitochondrial stress, and energy imbalance in metabolic cells and immune cells triggers proinflammatory responses and metabolic disorders." (PMID 38164186, 2024). "Although we found that the skeletal muscle cGAS-STING pathway was not the underlying cause of metabolic disorders, whether it plays a role in the amelioration of metabolic disorders is unknown, and we performed further validation." (PMID 37762143, 2023). "However, we had not yet found a correlation between HFD-induced metabolic disorders and the cGAS-STING signaling pathway in skeletal muscle." (PMID 37762143, 2023). "Therefore, the dysregulation of the cGAS-STING signaling pathway may lead to excessive inflammatory response and then participate in the development of various metabolic diseases such as T2DM, tumors, and neurodegenerative diseases." (PMID 37762143, 2023). "Exercise is an effective intervention protecting against metabolic diseases, however, the role of the cGAS-STING signaling pathway in this process is unclear, and the effect and mechanism of different exercise intensities on metabolic disorders are still unknown." (PMID 37762143, 2023).
inflammation (14 papers, 2021 to 2026). Aberrant reaction of the microcirculation characterized by movement of fluid and leukocytes from the blood into extravascular tissues. "Overall, cGAS deficiency was correlated with a lower level of rabies-induced brain inflammation and a similar level of systemic inflammation compared with infected WT mice." (PMID 41300373, 2025). "Deficiency in cGAS or STING ameliorates silica-induced lung inflammation." (PMID 34218252, 2021). "This study examined the role of the cGAS‒STING pathway in retinal inflammation via bulk RNA sequencing." (PMID 41487469, 2026). "Further, blocking cGAS function with the specific inhibitor RU.521 protected mice from birch pollen allergen-induced airway inflammation and type-2 immune responses." (PMID 40276777, 2025). "Specifically, pharmacological inhibition enabled a targeted and temporal control of cGAS activity, thus reducing potential confounding effects on immune maturation and allowing us to study cGAS role in airway inflammation in a more precise manner." (PMID 40276777, 2025). "Taken together, these data suggest that microbial DNA induces ageing-related cardiac inflammation through the activation of cGAS/STING signaling." (PMID 37520546, 2023). "In addition, further research has provided insights into the involvement of the cGAS/STING signalling pathway in the context of liver inflammation, highlighting its importance in the release of inflammatory mediators and its impact on liver pathologies." (PMID 39301315, 2024). "Here, we blocked cGAS function with the specific inhibitor RU.521,20 which protected mice from BPE allergen-induced airway inflammation and type 2 immune responses." (PMID 40276777, 2025). "Given the involvement of the cGAS‐STING pathway in inflammation, senescence and disease, inhibitors of cGAS or STING could potentially be used to treat age‐related chronic inflammation in A‐T patients." (PMID 37254625, 2023). "SARS-CoV-2 as RNA-virus activates cGAS– stimulator of interferon genes (STING) signaling in endothelial cells through mitochondrial DNA release, which leads to type I IFN production, and pharmacological inhibition of STING reduces severe lung inflammation and disease severity." (PMID 36773052, 2023).
neurological diseases (12 papers, 2020 to 2026). "Given the exciting progress in the development of cGAS inhibitors and safety profile of genetic models with cGAS loss of function, we believe that cGAS inhibitors hold great therapeutic potential for various neurological disorders." (PMID 37941028, 2023). "Since much of the AGS pathology is centered in the brain, it is of great value to use neural tissue and/or models that express the AGS neurological disorders to examine the nucleic acid machinery and its association to cGAS activation." (PMID 32244340, 2020). "Recent studies suggest that leaked mtDNA also serves as an important trigger that activates cGAS pathway, which contributes to the inflammatory diseases, neurological diseases, and fibrotic conditions." (PMID 38766643, 2024). "While mitochondrial deoxyribonucleic acid (mtDNA) and cyclic GMP-AMP synthase (cGAS) are recognized for inducing inflammation in various neurological disorders, their involvement in NeP remains ambiguous." (PMID 38840892, 2024). "In this review, we summarize the latest developments on the cGAS-STING DNA-driven immune response in various neurological diseases and conditions." (PMID 37941028, 2023). "Activation of the cGAS–STING signaling pathway by cytoplasmic DNA plays an important role in the occurrence and progression of several neurological diseases." (PMID 38525112, 2024). "The future of cGAS-STING research in the CNS holds great promise for advancing our understanding and improving patient outcomes in the field of neurological disorders." (PMID 37941028, 2023). "The cGAS-STING pathway has emerged as a critical player in the CNS, contributing to various neurological disorders characterized by chronic neuroinflammation." (PMID 37941028, 2023). "The cGAS-STING axis, a cytoplasmic pathway responsible for detecting dsDNA, plays a significant role in mediating neuroinflammation in neurological diseases." (PMID 37770901, 2023). "Finally, we lay out the current advancements in research and development of cGAS inhibitors and assess the prospects of targeting cGAS and STING as therapeutic strategies for a wide spectrum of neurological diseases." (PMID 37941028, 2023). "The ability of AIM2 to recognize dsDNA in conjunction with the cGAS-STING pathway and initiate inflammasome assembly underscores its importance in neuroinflammatory processes, highlighting its potential as a therapeutic target in various neurological disorders." (PMID 40781073, 2025). "Given the expanding roles of cGAS-STING signalling in neurodegeneration, our study uncovers mechanistic insights into inflammatory mechanisms not just in A-T, but more broadly in neurological diseases associated with genome instability and excessive interferon production in the CNS." (PMID 38084916, 2024).
heart disease (7 papers, 2021 to 2025). "It is recognised that sterile inflammation initiated by the cGAS-STING pathway is a key driver of many heart diseases, and targeting inflammation has emerged as a potential therapeutic strategy." (PMID 40245468, 2025). "Given the wealth of preclinical data attesting to the importance of cGAS-STING in the pathogenesis of cardiac disease, it will be interesting to see if any of these medicinal chemistry breakthroughs reach the clinical trial arena for this indication." (PMID 38665231, 2024). "There has been substantial recent interest in the role that cGAS-STING pathway activation plays in organ injury, and the literature describing the contributions of cGAS-STING to heart disease is reviewed in the relevant section later in this review." (PMID 38665231, 2024). "Recent studies have found that the cGAS–STING signaling pathway plays an important role in the pathology of various heart diseases." (PMID 38525112, 2024). "In conclusion, the cGAS–STING signaling pathway plays a significant role in aggravating heart disease." (PMID 38525112, 2024). "Activation of the cGAS–STING signaling pathway by ER stress is thought to be a key mechanism in the progression of heart disease." (PMID 38525112, 2024). "ER stress has also been suggested as a crucial mechanism for the role of the cGAS–STING pathway in cardiac diseases." (PMID 34906241, 2021). "This study did not further confirm the link between mtDNA and cGAS–STING pathway in animal models, but the results of this experiment also provide ideas for the mechanism of cGAS–STING pathway activation in heart disease." (PMID 34906241, 2021). "Given the impressive performance of the cGAS–STING pathway in inflammation, many research groups have directed their work to the function that the cGAS–STING pathway performs in different cardiac diseases." (PMID 34906241, 2021). "Several therapeutic options targeting the cGAS-STING pathway were explored in heart disease models." (PMID 40245468, 2025). "Experimental studies implicating the cGAS-STING pathway in heart disease." (PMID 38665231, 2024). "However, the underlying mechanism is very complex, and in‐depth research is needed to clarify the role of the cGAS–STING signaling pathway in heart disease progression." (PMID 38525112, 2024). "These experimental results suggest that the cGAS–STING pathway may be involved in cardiac disease by altering macrophage polarity." (PMID 34906241, 2021). "In the next step, we explored how the cGAS/STING pathway could be modulated by specific agonists and antagonists in the context of cardiac disease." (PMID 40497954, 2025). "In addition to dynamic control of G protein signaling, cytosolic DNA is sensed and transduced into an inflammatory transcriptional output through palmitoylation-dependent activation of the cGAS-STING pathway, which has been targeted pharmacologically in preclinical models of heart disease." (PMID 38385554, 2024). "To further clarify the molecular mechanism by which the cGAS-STING signaling pathway regulates DCM heart function, we focused on pyroptosis, a type of programmed cell death that is closely related to oxidative damage and plays an important role in the process of heart disease." (PMID 35538059, 2022).
immune diseases (7 papers, 2021 to 2025). "It is believed that suramin and aspirin may be used as cGAS inhibitors to treat DNA-mediated immune diseases based on these pharmacological findings." (PMID 34867409, 2021). "Additional enrichments are for Reactome pathways related to the immune system, including “cyclic GMP-AMP synthase (cGAS)-stimulator of interferon genes (STING) mediated induction of host immune responses” (B&H FDR adjusted p < 0.005) and Reactome’s “diseases of immune system” (p < 0.02)." (PMID 38632500, 2024).
liver (6 papers, 2021 to 2025). "The cGAS-STING pathway has been shown to be a promising target for the treatment of gastrointestinal tumors." (PMID 40621423, 2025). "We previously showed that oxidative stress induces mitochondrial injury and mtDNA release to promote cGAS-STING activation in macrophages during liver IR injury." (PMID 36765043, 2023). "MLKL knockout (KO) attenuated liver IR injury and suppressed the activation of cGAS-STING signaling in intrahepatic macrophages, which was abrogated by STING activation with its agonist." (PMID 36765043, 2023). "MLKL deficiency promoted mitophagy activation to reduce oxidative DNA injury in hepatocytes, which suppressed the activation of cGAS-STING signaling in macrophages, leading to attenuated liver IR injury." (PMID 36765043, 2023).
renal diseases (6 papers, 2021 to 2026). "Interestingly, the cGAS-STING signaling pathway not only is implicated in the progression of PF but also plays a role in the development of various kidney diseases." (PMID 40877559, 2025). "Recent research has underscored the pivotal role of cGAS‐STING pathway in renal diseases, highlighting its promise as a potential target for therapeutic intervention." (PMID 40008481, 2025). "Consistent with this notion, dysregulation of the cGAS‒STING signaling pathway in adipocytes, hepatocytes, and renal proximal tubule epithelial cells are associated with metabolic dysfunction, impaired energy homeostasis, and kidney diseases." (PMID 34665236, 2021). "cGAS-STING-mediated sterile inflammation in liver and kidney diseases and aging warrants further exploration in clinical settings." (PMID 39114669, 2024).
vasculopathy (5 papers, 2018 to 2026). "Recent studies have found that gain-of-function mutation of STING leads to vasculopathy and apoptosis-derived membrane vesicles in SLE serum to induce type I interferon production through activation of the cGAS–STING pathway." (PMID 33901014, 2021).
adenocarcinoma (4 papers, 2022 to 2025). A common cancer characterized by the presence of malignant glandular cells. "To test if class A ODNs regulate the cGAS level in other cell types, we treated Raw264.7 cells, a mouse macrophage cell line, and MC38, a mouse adenocarcinoma cell line, with PBS control, LPS, ODN1826, ODN1585, and ODN2216 for 18 h." (PMID 40337520, 2025).
blood disorders (3 papers, 2023 to 2026). "In this review, we integrate mechanistic, preclinical, and clinical evidence across solid tumors and hematologic malignancies to delineate the roles of cGAS-STING as both a prognostic biomarker and a therapeutic target." (PMID 42311657, 2026). "Dead-box helicase 41 (DDX41), a helicase, not only unwinds DNA-RNA hydrids but also activates the cGAMP synthase (cGAS)-Stimulator of Interferon Genes (STING) pathway in blood disorders." (PMID 40061014, 2025).
central nervous system diseases (3 papers, 2021 to 2025). "Recent studies have linked cGAS‐STING activation to several neuroinflammatory conditions, supporting its role as a critical regulator of inflammation in central nervous system disorders." (PMID 40522023, 2025). "Here, we present a review of recent advances in the literature on cGAS-STING signaling and provide a comprehensive overview of the modulatory patterns of the cGAS-STING pathway in CNS disorders." (PMID 34631213, 2021). "To date, studies of the cGAS-STING pathway in CNS disorders have predominantly been conducted in preclinical settings, and further studies are necessary to explore the clinical relevance of this pathway." (PMID 34631213, 2021). "In the following text, we discuss the role of cGAS-STING signaling in CNS disorders." (PMID 34631213, 2021). "Research on the role of the cGAS-STING pathway in CNS disorders has grown in recent years." (PMID 34631213, 2021). "In this review, we summarize the recent advances in cGAS-STING signaling, and its crucial role in the pathogenesis of CNS disorders." (PMID 34631213, 2021). "In this review, we present recent advances in the literature on cGAS-STING signaling, focusing on the contribution of the cGAS-STING axis to CNS disorders." (PMID 34631213, 2021). "Understanding and regulating the interactions between cGAS-STING signaling and the nervous system may thus provide an effective approach to prevent or delay late-onset CNS disorders." (PMID 34631213, 2021).
intestinal diseases (3 papers, 2023 to 2026). "This review aims to provide insight into recent findings of the protective and detrimental roles of the cGAS-STING pathway in intestinal diseases." (PMID 37781354, 2023). "However, opposite perspectives exist regarding the role of the cGAS-STING pathway in different intestinal diseases." (PMID 37781354, 2023). "A thorough exploration of the molecular mechanisms and regulatory networks of the cGAS-STING signaling pathway offers a significant theoretical foundation and potential treatment targets for developing novel strategies to treat intestinal diseases." (PMID 41624832, 2026).
respiratory diseases (3 papers, 2023 to 2025). "Traditional Chinese medicine can treat or alleviate respiratory diseases by regulating the cGAS-STING signaling pathway." (PMID 39737190, 2024). "This systematic review highlights the molecular mechanisms governing cGAS-STING activation, its interaction with lung pathogens, and its potential as a therapeutic agent in respiratory diseases." (PMID 40697819, 2025).
digestive diseases (2 papers, 2025). "In this review, the role of cGAS-STING pathway in digestive diseases was discussed." (PMID 40621423, 2025). "In addition, we systematically summarized recent advances in the treatment of gastrointestinal disorders with phytochemicals that target the cGAS-STING pathway." (PMID 40621423, 2025). "Summary of herbal active ingredients that regulate the cGAS-STING pathway in digestive diseases." (PMID 40621423, 2025). "Therefore, targeting the cGAS-STING pathway is a potential therapeutic strategy for digestive diseases." (PMID 40621423, 2025). "Notably, emerging evidence suggests that specific herbal active compounds may alleviate digestive diseases by modulating the cGAS-STING pathway." (PMID 40621423, 2025).
gastrointestinal disease (2 papers, 2025). A disease that occurs in the gastrointestinal system, excluding the hepatobiliary system. "Dysregulation of the cGAS-STING pathway has been demonstrated to be an important pathogenetic mechanism in diverse gastrointestinal diseases." (PMID 40621423, 2025). "In addition, we thoroughly reviewed the potential of natural plant compounds that target the cGAS-STING pathway for the treatment of gastrointestinal diseases." (PMID 40621423, 2025). "The cGAS-STING signaling pathway demonstrates markedly diverse and sometimes contradictory functions across various hepatic and gastrointestinal diseases." (PMID 41041344, 2025). "This review seeks to systematically elucidate the role of the cGAS-STING signaling pathway in a range of hepatic and gastrointestinal diseases." (PMID 41041344, 2025).
myopathies (2 papers, 2020 to 2025). "In summary, we observed elevated mtDNA-mediated TLR9/NF-κB and cGAS-STING inflammatory signalling in a patient harbouring the uncharacterized MFN2 Q367H variant who displayed late-onset myopathy as a standalone phenotype." (PMID 40175090, 2025). "As elevated inflammation can cause myopathy, our findings linking the Q367H MFN2 variant with elevated TLR9 and cGAS-STING signalling can explain the patient’s myopathy." (PMID 40175090, 2025). "Whether cGAS-STING signalling further perturbs pathology remains to be determined, though elevated cGAS-STING inflammation is also linked to myopathy." (PMID 40175090, 2025). "Arguing that activation of TLR9-mediated inflammation is a general response to loss of mitochondrial fusion, loss of the inner mitochondrial membrane fusion protein OPA1 in muscle leads to TLR9-mediated NF‐κB activation (but not cGAS-STING), where it also drives an inflammatory myopathy." (PMID 40175090, 2025).
retinopathy (2 papers, 2022 to 2023). "In this work, we found that the cGAS-STING pathway was activated in the retina with ischemia-induced retinopathy, predominantly in myeloid cells." (PMID 36409895, 2022). "Therefore, considering our scRNA-seq findings that cGAS-STING components are enriched in retinal microglia/macrophages, suppressing cGAS-STING in retinal microglia/macrophages cells may be beneficial in treating retinal degenerative diseases and retinopathy." (PMID 37217935, 2023).